PLA2G7 (phospholipase A2 group VII)
Diseases named in the same sentence as PLA2G7 in open-access papers (continued):
Sharing a sentence is not in itself a finding about the gene and the disease.
hepatocellular carcinoma (4 papers, 2025). A malignant tumor that arises from hepatocytes. "In hepatocellular carcinoma, PLA2G7-high macrophages represent a highly immunosuppressive subset that hinders CD8+ T-cell activation, suggesting PLA2G7 as a key factor in tumor immune regulation." (PMID 40169540, 2025). "For example, in hepatocellular carcinoma, PLA2G7 promotes cancer cell development through the STAT1/PD-L1 axis, and high expression of PLA2G7 in macrophages can promote immunosuppression by adversely affecting the activation of CD8+ T cells." (PMID 40169540, 2025). "In one study on hepatocellular carcinoma, it was shown that macrophages expressing PLA2G7 form a subset of highly immunosuppressive cells that hinder the activation of CD8 T cells." (PMID 41030501, 2025). "Furthermore, macrophages with high levels of PLA2G7 in hepatocellular carcinomas have a strong immunosuppressive effect, inhibiting the activation of CD8+ T lymphocytes, indicating a key role of PLA2G7 in modulating the immune response around the tumor." (PMID 40869314, 2025). "Notably, the immunosuppressive PLA2G7high macrophages impeded CD8 T-cell function, and inhibition of PLA2G7 by darapladib enhanced the efficacy of anti-PD-1 antibody immunotherapy in hepatocellular carcinoma (HCC) mouse models." (PMID 40136470, 2025).
influenza (4 papers, 2010 to 2021). An acute viral infection of the respiratory tract, occurring in isolated cases, in epidemics, or in pandemics; it is caused by serologically different strains of viruses (influenzaviruses) designated A, B, and C, has a 3-day incubation period, and usually lasts for 3 to 10 days. "Notable among immune-related positional candidates are Tnfrsf21, and Pla2g7 implicated in influenza control, though its effect was limited to male mice." (PMID 26845690, 2016). "Conversely, only about 20.00% PLA2G7 positive rates were observed in patients with influenza infection." (PMID 33762651, 2021). "The positive rate of PLA2G7 in nasal swabs from donors with pneumonia was higher than that in health controls and patients suffered seasonal influenza infection." (PMID 33762651, 2021).
intestinal polyposis (4 papers, 2020 to 2025). "Depletion of PLA2G7 reduced intestinal polyposis and tumorigenesis in APC (Min/+) mice." (PMID 37704909, 2023).
pancreatic cancer (4 papers, 2021 to 2025). "Elevated PLA2G7 levels have been found in patients with cachexia as well as colorectal and pancreatic cancer." (PMID 40869314, 2025). "Importantly, PLA2G7 levels were also increased in colorectal and pancreatic cancer patients with CCx." (PMID 34427055, 2021). "High PLA2G7 expression and secretion were hallmarks of cachexia‐inducing cancer cell lines, and elevated circulating levels of PLA2G7 were a robust marker of CCx in different types of malignancies such as colorectal, lung, and pancreatic cancers." (PMID 34427055, 2021).
thrombosis (4 papers, 2016 to 2022). "Furthermore, another potential effect of PLA2G7 in CCx relates to cachexia‐associated thrombosis." (PMID 34427055, 2021).
lung fibrosis (3 papers, 2022 to 2025). "Specific deletion of Pla2g7 in macrophages effectively inhibited pulmonary fibrosis in silicosis model mice and reduced the proportion of SiglecFloAMs." (PMID 40389600, 2025).
metastatic tumor (3 papers, 2011 to 2021). "Finally, PLA2G7 encodes a lipoprotein-associated phospholipase that regulates epithelial-mesenchymal transition, and it is associated with the development of metastatic disease in solid organ cancer." (PMID 33809641, 2021).
bladder cancer (2 papers, 2025). "To elucidate the mechanisms underlying PLA2G7 overexpression in bladder cancer, we initially examined genomic alterations, including copy number variations (CNVs) and methylation status of PLA2G7 within TCGA bladder cancer data." (PMID 40169540, 2025). "In this study, we found that PLA2G7 is overexpressed in bladder cancer and significantly associated with worse prognosis." (PMID 40169540, 2025). "Immunohistochemical testing indicated that PLA2G7 is significantly overexpressed in bladder cancer, and increased PLA2G7 expression is significantly associated with higher tumor stage." (PMID 40169540, 2025). "We also demonstrated that the transcription factor ETS1 promotes PLA2G7 expression in bladder cancer." (PMID 40169540, 2025). "To investigate the functional role of ETS1 in regulating PLA2G7 expression, we established bladder cancer cell lines with stable ETS1 knockdown." (PMID 40169540, 2025). "To further investigate the role of PLA2G7 in bladder cancer, we constructed stable PLA2G7 knockdown 5637 and T24 cell lines." (PMID 40169540, 2025). "Based on these results, we suggest that PLA2G7 can promote PD-L1 expression and immune evasion in bladder cancer." (PMID 40169540, 2025). "Collectively, these findings indicate that ETS1 positively regulates PLA2G7 expression in bladder cancer, thereby contributing to immune evasion." (PMID 40169540, 2025). "Further analysis of TCGA expression data revealed a significant positive correlation between ETS1 and PLA2G7 as well as PD-L1 expression in bladder cancer tissues." (PMID 40169540, 2025). "Treatment with the PLA2G7 inhibitor darapladib significantly impaired the tumorigenic capacity of bladder cancer cells in immunocompetent mice." (PMID 40169540, 2025). "We first analyzed PLA2G7 expression in bladder cancer using data from the TCGA database and found that PLA2G7 is elevated in bladder cancer compared to normal bladder tissues." (PMID 40169540, 2025). "Further analysis revealed that PLA2G7 depletion significantly inhibits PD-L1 expression in bladder cancer cells and suppresses tumor growth in vivo." (PMID 40169540, 2025). "In this study, we found that PLA2G7 is significantly elevated in bladder cancer and correlates with worse prognosis." (PMID 40169540, 2025). "We then constructed bladder cancer cells with stable overexpression of PLA2G7." (PMID 40169540, 2025). "Overexpression of PLA2G7 in bladder cancer was also observed in RT-qPCR results." (PMID 40169540, 2025). "Additionally, Western blot analysis of bladder cancer and normal tissues as well as normal bladder cell line and bladder cancer cell lines revealed elevated PLA2G7 expression in bladder cancer." (PMID 40169540, 2025). "We further investigated the effect of the PLA2G7 inhibitor darapladib on bladder cancer cells." (PMID 40169540, 2025). "Our results suggested that PLA2G7 depletion inhibits PD-L1 expression in bladder cancer cells." (PMID 40169540, 2025). "We next explored the effect of PLA2G7 on bladder cancer tumor immunity and PD-L1 expression." (PMID 40169540, 2025). "However, the role of PLA2G7 in bladder cancer and tumor immunity is still unclear." (PMID 40169540, 2025). "In addition, we found that ETS1 promotes PLA2G7 overexpression in bladder cancer cells." (PMID 40169540, 2025). "In summary, our study suggests that ETS1-mediated overexpression of PLA2G7 can regulate the phosphorylation of STAT1 and STAT3, leading to PD-L1 overexpression and promoting immune evasion in bladder cancer." (PMID 40169540, 2025). "This study revealed that PLA2G7 regulates the JAK-STAT pathway to promote PD-L1 expression and immune evasion in bladder cancer." (PMID 40169540, 2025). "MTS assay results indicated that PLA2G7 knockdown did not significantly affect bladder cancer cell proliferation." (PMID 40169540, 2025). "In vitro experiments suggested that PLA2G7 knockdown does not significantly affect bladder cancer cell proliferation, migration, or invasion." (PMID 40169540, 2025).
bladder cancer (continued). "In vitro experiments demonstrated that knockdown of PLA2G7 does not significantly affect the proliferation, migration, and invasion of bladder cancer cells." (PMID 40169540, 2025). "Wound healing and transwell assays also demonstrated that PLA2G7 knockdown did not significantly affect bladder cancer cell migration and invasion." (PMID 40169540, 2025).
Cachexia (2 papers, 2021 to 2025). Severe weight loss, wasting of muscle, loss of appetite, and general debility related to a chronic disease. "Whether PLA2G7 might prevent or worsen cachexia‐associated thrombosis through PAF hydrolysis or generation of pro‐inflammatory lipid species, respectively, is unknown." (PMID 34427055, 2021). "To assess further the biomarker potential of PLA2G7 in CCx, we performed a longitudinal prospective study in which we monitored circulating PLA2G7 levels in the course of cachexia development." (PMID 34427055, 2021). "Circulating PLA2G7 levels gradually rose during cachexia development." (PMID 34427055, 2021). "Furthermore, circulating PLA2G7 levels progressively rise during cachexia development and are already increased in pre‐cachectic tumour‐bearing animals, suggesting that PLA2G7 could be an early marker of the disease (i.e. before onset of body weight loss)." (PMID 34427055, 2021).
melanoma (2 papers, 2020). A malignant, usually aggressive tumor composed of atypical, neoplastic melanocytes. "Several PLA2 isoforms, i.e., pla2g6, pla2g7 and pla2g10, appeared to be upregulated in zebrafish V12RAS-driven melanoma, and PLA2G6 gene was associated with melanoma risk in humans." (PMID 33121001, 2020).
nasopharyngeal carcinoma (2 papers, 2016 to 2021). A carcinoma arising from the nasopharyngeal epithelium. "In nasopharyngeal carcinoma (NPC) cells, there is evidence that PLA2G7 can enhance tumor cell migration and survival, and similar findings have also been observed in PCa cells." (PMID 34404374, 2021).
pneumonia (2 papers, 2021). An acute, acute and chronic, or chronic inflammation focally or diffusely affecting the lung parenchyma, caused by an infection in one or both of the lungs (by bacteria, viruses, fungi, or mycoplasma.). "The expression profile of PLA2G7 was observed in patients with pneumonia could help to understand patho-mechanisms underlying pneumonia and CVDs." (PMID 33762651, 2021). "Notably, ΔCt of PLA2G7 in group with severe pneumonia were lower than that in group with moderate pneumonia (P value = 1.6e − 8), indicating PLA2G7 could be associated with the severity of pneumonia." (PMID 33762651, 2021). "PLA2G7 has also been recently proposed as biomarker for COVID‐19‐related and pneumonia‐related cardiovascular complications." (PMID 34427055, 2021). "The ΔCt of PLA2G7 in group of SARS-CoV-2 shared a similar pattern to that in group of moderate pneumonia." (PMID 33762651, 2021). "It was worth of noting that 100% positive rate of PLA2G7 were observed in severe pneumonia." (PMID 33762651, 2021). "In addition, the ΔCt of PLA2G7 were lower in severe pneumonia than in moderate pneumonia (P value = 1.6e − 8)." (PMID 33762651, 2021). "Notably, 100.00% of PLA2G7 positive rates were seen in group of severe pneumonia while 65.00% were noticed in moderate pneumonia patients." (PMID 33762651, 2021). "Surprisingly, a similar high detection rate of PLA2G7 was seen in patients with pneumonia (SRAS-CoV-2 negative)." (PMID 33762651, 2021). "In addition, the plasma levels of PLA2G7 in pneumonia patients were also not tested." (PMID 33762651, 2021).
prostate tumors (2 papers, 2011 to 2019). "PLA2G7 was expressed in 50.0% of the primary prostate tumor samples, whereas only 2.7% of the adjacent normal tissues showed any staining." (PMID 22202492, 2011). "Tissue microarray (TMA) containing samples from primary prostate tumors (n = 1137) along with adjacent normal tissues (n = 409) was utilized to study PLA2G7 expression in prostate tissues." (PMID 22202492, 2011). "This hypothesis is further supported by our previous results demonstrating PLA2G7 protein expression in 70% of metastatic prostate tumors compared to the 50% positivity observed in the primary tumors." (PMID 22202492, 2011). "In addition, seven other genes, GGT1, HDAC1, KLK2, MYO6, PLA2G7, BICD1, and CACNAID, were found to be differentially expressed in prostate tumors of non-BCR and BCR patients." (PMID 31741711, 2019).
sarcoidosis (2 papers, 2020 to 2024). Sarcoidosis is a multisystemic disorder of unknown cause characterized by the formation of immune granulomas in involved organs. "In contrast, both Mac 1 and Mac 2 in sarcoid granulomas adopted an inflammatory state with sarcoidosis-specific gene activation, including CHIT1, PTGDS, and PLA2G7." (PMID 39225100, 2024). "According to Gini score calculated from gene expression values, we examined the top-6 most important AA metabolism-related genes (including PLA2G6, PLA2G7, AKR1C1, AKR1C3, LTA4H, and PTGER4) in sarcoidosis, whose expression showed a positive correlation with sarcoidosis samples." (PMID 33097805, 2020).
Anxiety (1 paper, 2025). Intense feelings of nervousness, tension, or panic often arise in response to interpersonal stresses. "Notably, 6.7% (3 genes) - Glb1, Pla2g7 and Shbg - of the investigated amygdala genes showed significant correlations with both anxiety measures and mPFC gene expression." (PMID 41173860, 2025).
autism (1 paper, 2016). Persistent deficits in social interaction and communication and interaction as well as a markedly restricted repertoire of activity and interest as well as repetitive patterns of behavior. "A meta-analysis based on differentially expressed genes in autism identified PLA2G7 as a genetic marker involved in the development and progression of child autism." (PMID 27716781, 2016).
B-cell lymphoma (1 paper, 2025). "The expression and activity of PLA2G7 are also linked to B-cell lymphoma in SS, suggesting its diagnostic utility in SS-related malignancies." (PMID 39928612, 2025).
benign concentric annular macular dystrophy (1 paper, 2008). Benign concentric annular macular dystrophy (BCAMD) is a progressive autosomal dominant macular dystrophy characterized by parafoveal hypopigmentation followed by a retinitis pigmentosa-like phenotype (nyctalopia and peripheral vision loss) with a bullBs eye configuration. "One of the genes, PLA2G7 (PAF-AH, Lp-PLA2), a candidate for a dominant form of macular dystrophy, benign concentric annular macular dystrophy (BCMAD), was selected for further study." (PMID 18776951, 2008).
cervical cancer (1 paper, 2023). A primary or metastatic malignant neoplasm involving the cervix. "A refined risk score model, comprising PLA2G7, TNF, TYK2, F2, and NRP1, effectively stratified cervical cancer patients into distinct risk groups." (PMID 37704909, 2023).
dermatitis (1 paper, 2025). An inflammatory process affecting the skin. "Supporting this supposition, inhibition of the PAF degradative enzyme, PLA2G7, exacerbated dermatitis, vascular leak and neutrophil infiltration while depletion of basophils, a major cellular source of PAF, ameliorated disease." (PMID 41279180, 2025).
leukopenia (1 paper, 2024). "However, it is known from single cell sequencing studies that both PLAC8 and PLA2G7 are expressed across a range of different white cell types, which would mitigate the effect of a selective leukopenia." (PMID 38592057, 2024).
Macular dystrophy (1 paper, 2008). Macular dystrophy is a nonspecific term for retinal degeneration, generally confined to the macula, usually presumed of genetic origin. "Pla2g7 (PAF-AH, Lp-PLA2), a possible candidate for a dominant form of macular dystrophy (BCMAD), was selected for further study." (PMID 18776951, 2008). "PLA2G7(phospholipase A2, group VII), the top-ranked gene, is localized within the BCMAD locus, a dominant form of macular dystrophy." (PMID 18776951, 2008).
nephrosclerosis (1 paper, 2022). Hardening of the kidney due to infiltration by fibrous connective tissue (fibrosis), usually caused by renovascular diseases or chronic hypertension. "Our findings also show that variability in the PLA2G4A and PLA2G7 gene loci was associated with several atherosclerotic features in nephrosclerosis patients, including the risk of an accelerated progression." (PMID 35586043, 2022). "We showed that SCARB1 for the risk of nephrosclerosis, PLA2G7 and, especially, PLA2G4A for the CV risk in these patients, are loci that harbor genetic variants whose identification could be of utility in the management of this CKD." (PMID 35586043, 2022). "Six tag-SNPs (one in PLA2G7 and five in PLA2G4A) had a significant impact on the risk of accelerated progression in nephrosclerosis patients after adjusting for confounding variables." (PMID 35586043, 2022). "We screened 1,209 nephrosclerosis patients and controls for 86 tag-SNPs that were identified in the SCARB1, PLA2G4A, and PLA2G7 gene loci." (PMID 35586043, 2022).
retinal degeneration (1 paper, 2008). Degeneration of the retina. "Herein, we found that tissue and plasma levels of Pla2g7 might be differentially regulated; retinal degeneration was only associated with tissue, but not plasma levels of this enzyme." (PMID 18776951, 2008).
silicosis (1 paper, 2025). Silicosis is a respiratory disease caused by breathing in (inhaling) silica dust. "We found that damaged mitochondria accumulate in MoMacs affected by silicosis and that the silencing of Pla2g7 mitigated SiO2-induced changes in ALCAT1 levels." (PMID 40389600, 2025). "In this study, we found that the expression level of cathepsin B was significantly reduced in Pla2g7 KO silicosis mice." (PMID 40389600, 2025). "Pla2g7 expression was specific to the fibrotic niche of silicosis, as demonstrated by the ST-seq data." (PMID 40389600, 2025). "We found that silencing Alcat1 did not affect PINK1 expression in the mitochondria of Pla2g7-overexpressing macrophages, indicating that CL-related mitochondrial autophagy pathways are influenced by Lp-PLA2 levels in silicosis, via PINK1/Parkin-dependent and PINK1/Parkin-independent pathways." (PMID 40389600, 2025).